ADIPOR1 (adiponectin receptor 1)
Diseases named in the same sentence as ADIPOR1 in open-access papers (continued):
Sharing a sentence is not in itself a finding about the gene and the disease.
colon cancer (7 papers, 2011 to 2020). "Serum leptin and AdipoR1 and AdipoR2 expression levels were found to be associated with lymph node involvement, and AdipoR1 expression was correlated with tumor size in colon cancer patients." (PMID 33167521, 2020). "The rs12733285C/T genotype and the A allele of rs1342387 (A/G or A/A) of ADIPOR1 are protective factors for CRC, while the rs266729G/C genotype and the G allele of ADIPOQ are risk factors for colon cancer." (PMID 33167521, 2020). "Results from an additional study demonstrated that adiponectin mediated AMPK activity via AdipoR1 and AdipoR2 in a colon cancer cell line." (PMID 26362652, 2015). "While data on AdipoR1/2 expression in other malignancies are limited, the receptors have been found in normal colon and colon cancer tissue as well as in gastrointestinal stromal tumors." (PMID 21974986, 2011). "Likewise, studies have established a relationship between the presence of AdipoR1 and a better diagnosis in gastric and colon cancers." (PMID 29311755, 2017). "However, the opposite evidence has shown that adiponectin plasma levels are inversely associated with the risk of CRC, and that adiponectin can suppress the cell proliferation of colon cancer via AdipoR1- and -R2-mediated AMPK activation." (PMID 21749709, 2011). "We conclude that the rs12733285C/T genotype and the carriage of the A allele of rs1342387 (A/G or A/A) in ADIPOR1 are the protective factors for CRC, while that rs266729G/C and G allele of ADIPOQ are the risk factors for colon cancer after excluding rectal cancer cases." (PMID 21749709, 2011). "However, in colon cancer cells, both AdipoR1 and AdipoR2 can transmit cytostatic effects." (PMID 21974986, 2011). "Adiponectin has been shown to suppress cell proliferation via activation of AdipoR1 and -R2 mediated 5' adenosine monophosphate-activated protein kinase (AMPK) in colon cancer cells." (PMID 26362652, 2015). "The anticancer role of ADIPOQ was mainly induced by its receptors, which have been demonstrated to repress colon cancer cell lines (including HCT116, HT29 and LoVo) proliferation via ADIPOR1- and -R2-mediated 5′-AMP -activated protein kinase (AMPK)." (PMID 22087284, 2011). "Previously studies have documented that ADIPOQ repressed colon cancer cell lines (including HCT116, HT29 and LoVo) proliferation via ADIPOR1- and -R2-mediated AMPK, whereas, knockdown of ADIPORs such as ADIPOR1 relieved the suppressive effect of ADIPOQ on the growth of cancer cells." (PMID 22087284, 2011). "This case-control study demonstrates that polymorphisms in ADIPOR1 (rs12733285, rs1342387) are associated with the decreased risk of CRC, and polymorphism in ADIPOQ (rs266729) is a risk for colon cancer but not for rectal cancer." (PMID 21749709, 2011).
colorectal cancer (7 papers, 2011 to 2023). A primary or metastatic malignant neoplasm that affects the colon or rectum. "Some work has concluded that certain ADIPOR1 variants, including rs1342387(G/A), protect against colorectal cancer, whereas a third study found that rs1342387(G/A) increases the risk of this cancer." (PMID 26047008, 2015). "Epidemiological studies have suggested that variants on adiponectin (ADIPOQ) and its receptor ADIPOR1 (adiponectin receptor 1) are associated with colorectal cancer (CRC) risk; however, the results were inconclusive." (PMID 25516230, 2014). "In the current study, we further evaluated the associations between the variants of ADIPOQ and ADIPOR1 and the colorectal cancer in a southeast Chinese population." (PMID 25516230, 2014). "Cumulative effect of risk factors of smoking, ADIPOQ rs1063538, BMI and ADIPOR1 rs1539355 in colorectal cancer susceptibility in combined study." (PMID 22087284, 2011). "In ever smokers carrying rs1063538 T allele, ADIPOR1 rs1539355 was the strongest effect associated factor, and the combination of ever smoking, rs1063538 T allele and rs1539355 G allele exhibited a second highest risk of colorectal cancer, with a 66.7% patient rate." (PMID 22087284, 2011). "Recently, ADIPOR1 and ADIPOR2 were discovered to be strongly linked to metabolic and immunological homeostasis in colorectal cancer." (PMID 36896172, 2023). "According to a study based on 369 patients, the overexpression of ADIPOR1 is related to lower overall survival outcomes in colorectal cancer." (PMID 36896172, 2023). "To evaluate the combined effect of multifactor associated with colorectal cancer risk, we summed the number of risk factors of smoking status, ADIPOQ rs1063538, BMI and ADIPOR1 rs1539355 in each individual and analyzed the resulting colorectal cancer risk." (PMID 22087284, 2011). "However, their relationship to the detoxification enzyme Glyoxalase (GLO)-I and Adiponectin receptors (AdipoR1, AdipoR2) in colorectal carcinoma (CRC) is currently understudied." (PMID 26931562, 2016). "In conclusion, our meta-analysis suggests that the ADIPOR1 SNP rs1342387(G/A), but not the SNPs rs12733285(C/T) or rs7539542(C/G), are associated with cancer risk, especially risk of colorectal cancer in Asians." (PMID 26047008, 2015). "Our meta-analysis suggests that the ADIPOR1 rs1342387(G/A) polymorphism, but not rs12733285(C/T) or rs7539542(C/G), may be associated with cancer risk, especially risk of colorectal cancer in Asians." (PMID 26047008, 2015). "For example, the expression of ADIPOR1 and ADIPOR2 are higher in colorectal carcinomas than in normal colonic epithelium." (PMID 21749709, 2011).
gastric cancer (7 papers, 2011 to 2025). A primary or metastatic malignant neoplasm involving the stomach. "Most previous studies on adiponectin and adiponectin receptors have focused on obesity-related diseases such as diabetes and metabolic syndrome; however, recent studies have implicated that AdipoR1 is also closely related to tumorigenesis such as breast, colorectal, and gastric cancer development." (PMID 39849382, 2025). "A recent clinical study analyzed ADPN's implication in gastric cancer progression evaluating the relation between AdipoR1/R2 expression and gastric intestinal metaplasia." (PMID 40452002, 2025). "AdipoR1 and AdipoR2 expression was significantly higher in peripheral blood of patients with gastric cancer compared to healthy subjects." (PMID 34063466, 2021). "The upregulation of AdipoR1 and AdipoR2 are reported in gastric carcinoma, whereas decreased in prostate cancer tissues compared with the nonmalignant tissues." (PMID 27119501, 2016). "The expression of these receptors has been reported in gastric cancer cell lines, and adiponectin has been shown to inhibit proliferation and peritoneal dissemination through AdipoR1/R2 activation on gastric cancer cells." (PMID 22078265, 2011). "In gastric cancer, adiponectin has the possibility to be involved in cell growth suppression via AdipoR1." (PMID 22078265, 2011). "Our data suggest that adiponectin has antiproliferative potential; however, AdipoR1 plays a more important role in increased survival in gastric cancer patients." (PMID 22078265, 2011). "AdipoR1 and AdipoR2 expression in gastric cancer cell lines (MKN45, TMK-1, NUGC3, and NUGC4) was evaluated by western blotting analysis, and the antiproliferative potential of adiponectin was examined in vitro." (PMID 22078265, 2011). "The protein expression of AdipoR1 and AdipoR2 was confirmed by immunostaining of surgically resected gastric cancer tissue specimens." (PMID 22078265, 2011). "In this study, we analyzed the correlation between serum adiponectin levels, expression of AdipoR1/R2, and clinicopathological characteristics as well as overall patient survival in gastric cancer." (PMID 22078265, 2011). "In this study, we evaluated expression levels of 2 adiponectin receptors--AdipoR1 and AdipoR2--and attempted to correlate their expression with prognosis in gastric cancer patients." (PMID 22078265, 2011). "Serum adiponectin levels were evaluated in 100 gastric cancer patients, and the expression of AdipoR1 and AdipoR2 was assessed by immunohistochemical staining." (PMID 22078265, 2011). "AdipoR1 and AdipoR2 have been identified in various tissues and cell types, and their expression has been reported in human lung, breast, pancreatic, colorectal, and gastric cancer tissues." (PMID 39849382, 2025). "Although further research in this field is necessary, the presence of AdipoR1 could be a novel anticancer therapeutic target in gastric cancer." (PMID 22078265, 2011). "Expression of AdipoR1 and clinicopathological characteristics in gastric cancer patients." (PMID 22078265, 2011). "By an immunohistochemical evaluation, a significantly lower AdipoR1/R2 expression in patients with gastric cancers was observed, as compared to patients with gastric intestinal metaplasia, suggesting that ADPN may have a role in gastric cancer progression as mediated by AdipoR1/R2 receptors." (PMID 40452002, 2025). "Furthermore, expression of AdipoR1 in gastric cancer cells assessed by immunohistochemical staining was associated with significantly longer survival rates in patients with gastric cancer in comparison to patients from negative staining group." (PMID 34063466, 2021). "The improvement of prognosis in gastric cancer patients with positive AdipoR1 expression might be affected by organ protective effects from insulin resistance and inflammatory states rather than as a result of a direct antiproliferative effect via globular adiponectin." (PMID 22078265, 2011).
gastric cancer (continued). "The presence of AdipoR1 could be a novel anticancer therapeutic target in gastric cancer." (PMID 22078265, 2011). "Although AdipoR1 and R2 are known as receptor subtypes, the relationship between gastric cancer and each subtype has not yet been clarified." (PMID 22078265, 2011). "In light of this observation, since various human gastric cancer cell lines, including MKN-28 cells, express both AdipoR1 and AdipoR2 receptors, we might presume a possible interaction between thaumatin-like protein 1a and the adiponectin receptor(s), as previously demonstrated for osmotin." (PMID 38276545, 2024). "Our clinical results reconfirm that AdipoR1 expression inversely correlates with tumor growth and might contributes to improvement of prognosis significantly, but not independently, in gastric cancer patients." (PMID 22078265, 2011). "However, multivariate analysis indicated that AdipoR1 was not an independent prognostic factor on patient's survival on gastric cancer." (PMID 22078265, 2011).
Hyperinsulinemia (7 papers, 2011 to 2019). An increased concentration of insulin in the blood. "The decreased adiponectin receptors may be due to hyperinsulinemia since it has been reported that insulin deficiency increased, but insulin replenishment decreased the expression of adipoR1/2 in animals in vivo." (PMID 22873349, 2012).
Hypertension (7 papers, 2015 to 2025). The presence of chronic increased pressure in the systemic arterial system. "The stage of hypertension (according to ABPM blood pressure classification) was associated with increased neutrophil AdipoR1 fluorescence intensity (AdipoR1 MFI) (P < 0.05)." (PMID 26146630, 2015). "Through molecular and rescue assays, we determined that NAT10 inhibits EndMT in hypertension through AdipoR1 mRNA ac4C acetylation, which is partly due to protection of endothelial function." (PMID 41254488, 2025). "Mechanistically, NAT10 inhibited endothelial dysfunction in hypertension through increased AdipoR1 mRNA ac4C acetylation." (PMID 41254488, 2025). "In summary, our study revealed that NAT10-induced ac4C acetylation of AdipoR1 mRNA inhibits EndMT in hypertension, which is partly due to the inhibition of endothelial dysfunction via increased mitochondrial biogenesis and function." (PMID 41254488, 2025). "Our results are consistent with those of a previous study that reported reduced expression of ADIPOQ and its receptors (AdipoR1 and AdipoR2) within the perivascular adipocytes of mice with angiotensin II-induced hypertension." (PMID 36157437, 2022). "We subsequently explored whether NAT10 inhibited endothelial dysfunction in hypertension in an AdipoR1-dependent manner." (PMID 41254488, 2025). "The mitochondrial tRNA 15910 C>T mutation may induce hypertension by changing the APN, AdipoR1, PGC-1α, and ERRα signaling pathways to elevate blood pressure." (PMID 33553162, 2020). "The stage of hypertension was associated with increased neutrophil but not monocyte AdipoR1 density (AdipoR1 MFI) (P < 0.05)." (PMID 26146630, 2015). "Herein, we explored the effect of NAT10-induced ac4C acetylation on endothelial dysfunction and EndMT in hypertension and clarified the mechanism through which the NAT10/ac4C/AdipoR1/PGC-1α axis inhibits endothelial dysfunction via the regulation of mitochondrial biogenesis and function." (PMID 41254488, 2025). "Thus, elucidating the pathological mechanism of the AdipoR1/PGC-1α axis may provide a novel therapy against endothelial dysfunction and EndMT in hypertension." (PMID 41254488, 2025).
Alzheimer disease (6 papers, 2017 to 2023). A progressive, neurodegenerative disease characterized by loss of function and death of nerve cells in several areas of the brain leading to loss of cognitive function such as memory and language. "AdipoRon improved cognitive dysfunction in a mouse model of Alzheimer's disease by activating the AdipoR1/AMPK pathway." (PMID 37077671, 2023). "Our findings revealed an increase in plasma adiponectin levels, enhanced methylation of the adiponectin gene promoter in peripheral blood, and elevated levels of AdipoR1 in PBMCs in persons with Alzheimer's disease." (PMID 36527105, 2022). "In addition, in a mouse model of Alzheimer's disease, the level of adiponectin in the cerebrospinal fluid decreased, while the expression of AdipoR1 in the brain increased." (PMID 37077671, 2023). "Osmotic proteins are able to encourage neurite outgrowth as well as synaptic complexity through AdipoR1 and NgR1 signaling, suggesting that AdipoR1 may be an available therapeutic target for neurodegenerative diseases like Alzheimer's disease." (PMID 34992508, 2021). "We report an altered metabolic environment in the brains of the 5XFAD mouse model of Alzheimer’s disease, where we observe significantly decreased neuronal expression of the adiponectin receptors AdipoR1 and AdipoR2, and overexpression of AdipoR2 in activated astrocytes." (PMID 32664663, 2020).
Anxiety (6 papers, 2019 to 2025). Intense feelings of nervousness, tension, or panic often arise in response to interpersonal stresses. "Similarly, dopamine neurons in the ventral tegmental area express AdipoR1 and loss of AdipoR1 pathway activity has been shown to increase dopamine activity and anxiety-like behaviours." (PMID 41463298, 2025). "We generated AdipoR1 conditional knockout mice and determined the impact of loss of AdipoR1 specifically in 5-HT neurons on depression- and anxiety-related behaviors, expression of key components of the 5-HT system and antidepressant responses in both male and female mice." (PMID 31980728, 2021). "Notably, AdipoR1 is predominantly expressed in serotonergic neurons, and its activation has been linked to better mood regulation and reduced anxiety and depression by enhancing neurogenesis, increasing serotonergic neurotransmission, and modulating neuroinflammatory processes." (PMID 40765030, 2025). "We have shown that AdipoR1 and AdipoR2 signaling in the hippocampus and ventral tegmental area are involved in the regulation of anxiety-related behavior and fear memories in a mouse model of post-traumatic disorder." (PMID 31980728, 2021). "Sex differences in adiponectin have been reported in both humans and mice, we therefore assessed the consequences of deletion of AdipoR1 in 5-HT neurons on depression- and anxiety-related behaviors in both male and female mice." (PMID 31980728, 2021). "In support of this notion, AAV-Cre-mediated deletion of AdipoR1 in the VTA of adult mice increases anxiety, implicating dysfunction of VTA adiponectin/AdipoR1 signaling as a possible mechanism underlying anxiety-like behavior." (PMID 29988086, 2019). "Recent research dissecting the role of adiponectin receptor in mediating anxiety reveals that intra-VTA infusion of adiponectin or the adiponectin receptor agonist AdipoRon suppresses dopaminergic neuron firing in an AdipoR1-dependent manner." (PMID 31718027, 2019). "Further investigation revealed that AdipoR1 on dopamine neurons is required for adiponectin action on spontaneous neuronal activity and anxiety-like behavior." (PMID 29988086, 2019). "The physiological importance of AdipoR1 in dopamine neurons in modulating anxiety-like behavior and neuronal activity was confirmed using a conditional knockout mouse model, in which AdipoR1 was deleted specifically in dopamine neurons." (PMID 29988086, 2019). "To determine whether AdipoR1 in 5-HT neurons regulate anxiety-related behaviors, we employed the approach-avoidance conflict tests." (PMID 31980728, 2021). "However, impaired adiponectin signaling due to adiponectin haploinsufficiency or AdipoR1 ablation increases dopaminergic activity and anxiety behavior." (PMID 31718027, 2019). "Another explanation is that anxiety behavior may be differentially regulated by AdipoR1 and AdipoR2." (PMID 29988086, 2019). "The present study provides evidence of 5-HT neurons as a neuronal substrate mediating the effects of adiponectin/AdipoR1 signaling on depression- but not anxiety-related behaviors." (PMID 31980728, 2021). "To determine the physiological relevance of adiponectin/AdipoR1 signaling in dopamine neurons to anxiety-related behavior, we generated mice lacking AdipoR1 specifically in dopamine neurons using the Cre–loxP system." (PMID 29988086, 2019).
endometrial cancer (6 papers, 2016 to 2025). Primary or metastatic malignant neoplasm involving the endometrium (mucous membrane that lines the endometrial cavity). "It has also been proven that reduced expression of AdipoR1 during the development of endometrial cancer is associated with an increase in the stage of endometrial cancer development and the occurrence of lymph node metastasis." (PMID 37190027, 2023). "We observed a heightened expression of ADIPOR1 in endometrial cancer tissue compared to the control benign endometrium." (PMID 40642843, 2025). "ADIPOR1 expression was elevated in grade 1 type 1 endometrial cancer, while ADIPOR2 was higher in type 2 cancers and showed similar levels in grade 1 and 2 cancers." (PMID 40642843, 2025). "The opposite associations of ADIPOR1 and ADIPOR2 with grade, histology, LVSI, and MELF underscore the complexity of these receptors' roles in endometrial cancer, warranting further exploration of their opposing functional implications." (PMID 40642843, 2025). "In endometrial cancer tissues, the expression of AdipoR1 is higher than that of AdipoR2." (PMID 31440472, 2019). "ADIPOR1 was significantly lower in patients without LVSI (p = 0.007), and leptin was significantly higher in patients with grade 2 endometrial cancer than grade 1 (p = 0.045)." (PMID 40642843, 2025).
endothelial dysfunction (6 papers, 2016 to 2025). In vascular diseases, endothelial dysfunction is a systemic pathological state of the endothelium (the inner lining of blood vessels) and can be broadly defined as an imbalance between vasodilating and vasoconstricting substances produced by (or acting on) the endothelium. "The results of this study indicated that resveratrol increased circulating adiponectin levels and protected against DN by ameliorating inflammation, oxidative stress, apoptosis and endothelial dysfunction via activating AMPK–SIRT1–PPARα through AdipoR1 and AdipoR2." (PMID 27286657, 2016). "Here we show that not only activation of AdipoR1 is necessary to restore NO-mediated FID, but decreased expression of AdipoR1 alone is sufficient to promote endothelial dysfunction." (PMID 35444544, 2022).